IL6 (interleukin 6)
Diseases named in the same sentence as IL6 in open-access papers (continued):
Sharing a sentence is not in itself a finding about the gene and the disease.
colitis (continued). "T-cell-specific ablation of Pros1 leads to a significant increase in the percentage of activated dendritic cells producing TNF-α and Interleukin-6 (IL-6) inflammatory cytokines, which, in colitis mouse models, conducts to pathological inflammation." (PMID 27775650, 2016). "DSS-colitis increased mRNA expression of interleukin IL-1a, IL-1b, IL-6, tumor necrosis factor TNFa, keratinocyte chemoattractant KC/CXCL1, granulocyte colony-stimulating factor, G-CSF and MCP-1." (PMID 27658624, 2016). "Intragastric administration of L. lactis MG1363 FnBPA+ (pValac::dts::IL-4) was able to decrease the severity of colitis, with animals showing decreased levels of IL-12, IL-6 and MPO activity; and increased levels of IL-4 and IL-10." (PMID 27576902, 2016). "The results revealed that Acer3 knockout significantly augmented the colitis-induced increases in the mRNA levels of Il-1β, Il-6, Tnf-α and Il-23a in colon, although Acer3 deficiency did not affect the basal mRNA levels of these inflammatory cytokines." (PMID 26938296, 2016). "Plasma levels of IL-6 in the colitis group were significantly higher than those in the control group, which was consistent with the results of the CD25 + Foxp3+ Treg analysis in rat peripheral blood cells." (PMID 27473867, 2016). "The IL6/STAT3 pathway activation has been shown to play a role in colitis by promoting inappropriate survival of T cells." (PMID 27525335, 2016). "The DSS colitis model has been characterized by increased serum levels of IL-6, IL-17, and TNFα and elevated levels of IL-4, IL-6, IL-10 and IFNγ have been reported in chronic colitis." (PMID 27177331, 2016). "Co-transfer of either CD4+CD45RBlo or Treg-of-B cells reduced the levels of IFN-γ, tumor necrosis factor (TNF)-α, IL-6, and IL-17 in the MLNs of mice with colitis." (PMID 27581189, 2016). "Strong correlation of HIF-1α mRNA level to GPx1, SOD1, and IL-6 mRNA expression suggests involvement of HIF-1α in transcriptional regulation of these genes during colonic inflammation and HBO2." (PMID 27656047, 2016). "The importance of IL-6 trans-signaling in the etiology of several chronic inflammations, such as asthma, colitis, and rheumatoid arthritis, has been well documented." (PMID 27350830, 2016). "Here we report that HBO2 significantly reduces severity of DSS-induced colitis, as evidenced by the clinical features, histological assessment, impaired immune cell expansion and mobilization, and reversal of IL-1β, IL-2, and IL-6 gene expression." (PMID 27656047, 2016). "MOS administration attenuated colitis-related increase of Coliforms, normalized colonic muc2 expression and attenuated local expression of proinflammatory cytokines IL-1a, IL1b, IL6, KC, G-CSF and MCP1 as well as toll-like receptor TLR4 and NLRP3 inflammasome." (PMID 27658624, 2016). "The administration of CBS effectively reduced the mRNA expression of TNF-α, IL-1β, and IL-6 in the colon tissue of mice with DSS-induced colitis." (PMID 26579201, 2015). "In this innate immune model of colitis, Tpl2−/− mice experienced milder colitis compared to wild type mice with reduced production of inflammatory cytokines IL-1α, IL-1β, IL-6, and IL-17, as well as reduced production of the anti-inflammatory cytokine IL-10." (PMID 25781948, 2015). "Cerebral IL-6 levels were increased in WAS-exposed animals with colitis in all brain regions examined compared to untreated WAS-exposed animals." (PMID 26066467, 2015). "Considering that TNBS instillation in mice induced an intense colon inflammation, we analyzed the local secretion of IL-1β, IL-6 and TNF-α." (PMID 25853847, 2015). "This is consistent with a previous report of diminished serum IL-6 and IL-17A levels in cd47-/- mice in a dextran sulfate-induced colitis model." (PMID 26010544, 2015).
colitis (continued). "Overall, these findings demonstrate that Tpl2 is dispensable for Th17 differentiation during a T cell transfer model of colitis where IL-6 and IL-23 have a dominant role but underscore the contribution of Tpl2 to Th1 differentiation in this model." (PMID 25781948, 2015). "The anti-inflammatory effects of oregano (carvacrol as major component) oil in mice with TNBS-induced colitis showed that some combinations lowered the amount of IL-1β and IL-6 cytokines." (PMID 28231227, 2015). "Acute DSS-induced colitis displayed a cytotoxic and chemotactic serum profile with significantly elevated levels of IL-6, IL-17 and KC (P = 0.008, P = 0.017 and P = 0.006, respectively)." (PMID 24414342, 2015). "Regarding expression of cytokines involved in epithelial cell dysregulation and damage, intestinal eosinophils expressed higher amounts of Tnf, Il6, and Il13 mRNA in colitis compared to uninflamed controls." (PMID 26200014, 2015). "The HAS3 null mice have the lowest DAI, the lowest colitis score, and the lowest circulating levels of the proinflammatory cytokine IL-6, compared to the wild-type, HAS1 null, and HAS1/3 null groups." (PMID 26448758, 2015). "Although our measurements for IL-6 under conditions of acute colitis exceeded the range of the assay, our data nevertheless suggest that both oral fucoidan extracts also reduce IL-6 levels, which would be consistent with previous observations." (PMID 26083103, 2015). "Weight loss, disease activity, colitis scoring, circulating IL-6 levels, and histology/immunostaining were all ameliorated in HAS3 null mice experiencing colitis." (PMID 26448758, 2015). "Administration of L. plantarum and L. brevis reduced IL1β, TNFα, and IFNγ, as well as the protein expressions of IL1β and IL6, and the signs of colitis in DSS-induced colitic mice." (PMID 26347738, 2015). "In HFD animals, the exercise significantly accelerated the healing of colitis, raised the plasma levels of IL-6 and irisin, downregulated the expression of IL-1β, TNF-α, and Hif1α, and significantly decreased the plasma IL-1β, TNF α, TWEAK, and leptin levels." (PMID 25684862, 2015). "Our results, in agreement with those of previous reports, demonstrated that IL-6 mAbs slightly attenuated DSS-induced colitis during the regeneration phase." (PMID 24993179, 2014). "We demonstrate that RasGRP3, a dominant member of RasGRPs in macrophages, impairs TLR3/4/9-induced IL-6 production and relieves dextrane sulphate sodium-induced colitis and collagen-induced arthritis." (PMID 25118589, 2014). "In contrast to this, male mice deficient in Il-6 in a DSS-induced colitis using lower concentrations of DSS, developed more severe colitis due to the increased death rate of intestinal epithelial cells." (PMID 24993179, 2014). "To functionally test if IL-6 was required only at the onset of colitis, we altered the timing of the first administration of anti-IL-6 mAb in triggered dnKO mice." (PMID 25478789, 2014). "Although R243 treatment reduced IL-10 secretion, its overall suppression of TNF-α and IL-6, together with inhibition of inflammatory cell infiltration, seemed to ameliorate colitis." (PMID 24714157, 2014). "Overproduction of proinflammatory cytokines, including TNF-α, IL-1β, and IL-6, is observed in several animal colitis models." (PMID 24995035, 2014). "The double-deficient mice should then lack the detrimental IL-6 signal and the beneficial alternate IL-6R ligand signal and, therefore, show normal susceptibility to DSS-induced colitis." (PMID 24993179, 2014). "In mice, IL-19 up-regulates TNFα and IL-6 expression and its deficiency increases susceptibility to DSS-induced colitis." (PMID 24718601, 2014). "We also performed coloscopy, immunohistochemistry, FITC-dextran measurements, ELISA for IL-6 and qPCR for various cytokines and other factors involved in colitis." (PMID 24993179, 2014).
colitis (continued). "The mild colitis group increased the expression of IL-6 about 2 folds (p<0.05) and the severe group increased about 5 folds (p<0.01) compared to the water group." (PMID 24504372, 2014). "Using two murine models of bowel injury – wound by biopsy and bacterial triggered colitis – we demonstrated that IL-6 is induced soon after injury by multiple cell types including intraepithelial lymphocytes." (PMID 25478789, 2014). "We found increased levels of IL-6 in the colon of mice fed L. lactis NCDO 2118 after colitis induction." (PMID 25110521, 2014). "It has been demonstrated that colitis in both humans and mice is associated with increased levels of cytokines such as TNF-α, IL-6, IL-12p70 and IL-23." (PMID 24722235, 2014). "In the present study, we analyzed IL-6 mAb-treated and Il-6r-deficient mice in a model of DSS-induced colitis." (PMID 24993179, 2014). "We performed immunofluorescence on colonic sections from dnKO mice six days post colitis induction using antibodies directed against IL-6 in combination with lineage markers." (PMID 25478789, 2014). "It has been demonstrated that TNFα, as well as other cytokines (IL-1β and IL-6) are elevated in colon tissue in response to DSS-induced colitis by our group and countless others." (PMID 25460165, 2014). "Pro-inflammatory cytokines such as TNFα, IL1β, and IL6 play pivotal roles in the pathogenesis of colitis." (PMID 25072851, 2014). "Our data suggest that IL-6 and IL-6R have an additional role in colitis, apart from the IL-6/IL-6R classic and trans-signaling." (PMID 24993179, 2014). "Sulfasalazine reduced DAI and IL-6 level in DSS-induced colitis mice under the same conditions, suggesting that hesperidin can be used to prevent colitis." (PMID 25045208, 2014). "Reduced colitis correlated with lower recruitment of neutrophils (p = 0.0018), as well as decreased production of IL-6 (p<0.0001), TNF (p = 0.0038), and IFN-γ (p = 0.0478)." (PMID 24992040, 2014). "The flavonoid hesperidin has also been shown to reduce DAI and IL-6 levels in DSS-induced colitis mice." (PMID 25045208, 2014). "Previous studies using dextran sodium sulfate and T cell transfer models of colitis suggested monocytes and T cells are the source of IL-6 during these injuries." (PMID 25478789, 2014). "We further showed that although the IL-6R is the only known receptor for IL-6, the LysMCre+/−/Il-6rfl/fl and Il-6r−/− mice and their littermate controls had the same susceptibility to DSS-induced colitis." (PMID 24993179, 2014). "Severe colitis was mediated by increased local expression of cytokines (IL-6, IL-10, TNF-α, IFN-γ and IL-17A) and phosphorylation of Leucine-rich repeat kinase 2 (LRRK2)." (PMID 24873968, 2014). "DSS-induced colitis, on its own, significantly increased the mRNA expression of Ifnγ, Il6, Il17 and Tgfβ as compared to controls." (PMID 24787575, 2014). "In spite of the fact that both doses decreased the production of IL-6 in the colon by more than 50%, only the higher dose significantly reduced the macroscopic and microscopic parameters of colitis." (PMID 23469045, 2013). "Elevated levels of IL-6 have been documented in a variety of autoimmune diseases, including rheumatoid arthritis, colitis, Crohn's disease, glomerular nephritis, and so forth." (PMID 24082909, 2013). "Specifically, treatment of mice with IL-4 or IL-10 resulted in a marked improvement in the histological appearance of the distal colon and suppression of Th1-cell type cytokines, such as IFN-γ, TNF-α and IL-6 in TNBS-induced murine colitis." (PMID 24314293, 2013). "Development of colitis has been shown to be inhibited by blocking production of IL-6, which encourages apoptosis of lamina propia autoreactive Th17 cells." (PMID 24454481, 2013). "Reduction in the severity of DSS colitis was associated with significantly lower MPO activity, as well as reduced IL-1β, IL-6 and IL-17 production in IL-13−/− mice." (PMID 24015275, 2013).
colitis (continued). "Pro-inflammatory cytokines such as TNF, IL-1 and IL-6, all regulated by the NF-κB pathway, have been shown to be overexpressed in colitis, gastritis, or hepatitis." (PMID 23117246, 2013). "In contrast, anti-IL-17A monoclonal antibody treatment was demonstrated to aggravate dextran sulfate sodium-induced colitis, and blockade of IL-17A in colitis of IL-10 knockout mice was inefficient in reducing disease unless IL-6 was also neutralized." (PMID 23956763, 2013). "Although the diversity of IL-6-dependent effects is extremely widespread, IL-6 has a protective effect during recovery from DSS-colitis because it promotes the survival of intestinal epithelial cells." (PMID 24046362, 2013). "To explore the effects of heat-killed VSL#3 on regular intestinal mucosal internal environment, we observed the level of the expression of IL-6/STAT3 trans-signaling related cytokines in large intestine from rats with colitis induced by dextran sulfate sodium." (PMID 24451125, 2013). "We then evaluated the expression of TNF-α, IL-1β, and IL-6 from each fraction to determine their relative contributions to mesenteric cytokine expression during acute colitis." (PMID 24386254, 2013). "DSS induced colitis also caused a 2-fold increase in the expression of TNF-α mRNA and 4- and 5- fold increases in the expression of IL-6 and IL-1β, respectively." (PMID 23469045, 2013). "It has been shown that selective blockade of TNF-α and IL-6 significantly decreases the severity of colitis and neutrophil/macrophage migration." (PMID 23818935, 2013). "Mice with colitis infected with H. polygyrus had higher concentrations of IL-6, IL-12p70, IL-10, IL-22 and MCP-1 but lower amounts of IL-17A (from 5.4 pg/mL to 3.2 pg/mL) at 6 DPI." (PMID 24167594, 2013). "We demonstrated a novel mechanism in which IL-6 increases S100A9 levels via STAT3 activation in CECs in an experimental murine model of DSS-induced colitis." (PMID 22962574, 2012). "Collectively, ADI-PEG was better tolerated in low dose and was more effective in normalizing SAA, plasma IL-6, and NO compared to high dose against colitis in animals." (PMID 22315509, 2012). "In the present study, we found increased IL-6 expression in CECs from mice with DSS-induced colitis and demonstrated directly that IL-6 induced S100A9 expression in both CECs from mice with colitis and in a human IEC cell line." (PMID 22962574, 2012). "RvD1 has been shown to reduce levels of TNF-α and IL-6 in mouse models of colitis, d-galactosamine-sensitized endotoxin shock and ALI." (PMID 23199346, 2012). "IL-6 has been linked to IBD pathogenesis and been suggested to play a pivotal role in colitis-associated CRC." (PMID 23109839, 2012). "Probiotic administration attenuated development of signs and symptoms of colitis, reduced colonic expression of TNFα, IL-6 and IFNγ and reserved colonic downregulation of PPARγ, PXR and FXR caused by TNBS." (PMID 21829567, 2011). "The proinflammatory cytokines IL-1β and IL-6 have been reported to be upregulated in the acute DSS colitis model." (PMID 21858054, 2011). "Intrarectal administration of poly P also suppressed the production of inflammatory cytokines IL-1β and IL-6 in mice colons with DSS-induced colitis." (PMID 21858054, 2011). "IL-6 has been shown to be involved in CD8-mediated colitis arising during lymphopenia in agreement with our data showing a role for IL-6 in TEM accumulation." (PMID 21423804, 2011). "It has been shown that selective blockade of IL-1R, CXCR2, CXCL1/KC, MCP-1, MIP-2, TNF-α and IL-6 significantly decreases severity of colitis and neutrophil/macrophage migration." (PMID 22073270, 2011). "Our findings agree with those in the literature suggesting that genes belonging to the IL-6 pathway are down-regulated in Resveratrol treated mice in experimental colitis and other inflammation models." (PMID 21151942, 2010).
colitis (continued). "Tissue levels of chlorotyrosine mirrored many cytokines (i.e. IL-6 and IL-17) that are in low abundance except during active inflammation making it an ideal biomarker of both neutrophil activation and colitis." (PMID 20976045, 2010). "In previous studies we were able to detect intestinal expression of TGF-β and IL-6 mRNA in mice suffering from colitis." (PMID 18545662, 2008). "Examination of IL-1β and IL-6 protein expression in our experimentconfirmed the best efficacy of the medium dose of thyme and oregano oilcombination in the suppression of colitis." (PMID 18288268, 2007). "Similarly, the concentrations of inflammatory factors in the blood of colitis mice in the A. actinomycetemcomitans gavage group were also significantly higher than those in the DSS group (IL-6, P = 0.002; IL-1β, P = 0.002; TNF-α, P = 0.004)." (PMID 41531455, 2026). "Moreover, IL-6 levels were lower in subacute betanin-supplemented rats compared to unsupplemented colitis-affected rats." (PMID 41515203, 2025). "Animal model studies of immune-related enterocolitis further showed that the IL-6 levels in intestinal tissues could initiate irAEs related colitis, while IL-6 inhibition simultaneously ameliorated neurotoxicity and enhanced antitumor immunity." (PMID 40519900, 2025). "Additionally, it is recognized as a potential inducer that leads to tumorigenesis from colitis through the IL-6/STAT3 (signal transducer and activator of transcription 3)/NF-κB (nuclear factor κB) signaling pathway." (PMID 40565156, 2025). "Additionally, it significantly affected the levels of inflammatory cytokines interleukin-6 (IL-6), interleukin-1β (IL-1β), and IL-10 in the colon, thus relieving inflammation in colitis mice." (PMID 40565286, 2025). "The expansion of MDSCs in the colon of mice with colitis was accompanied by increased GM-CSF and IL-6 in different IBD mouse models, suggesting that GM-CSF and IL-6 may be involved in MDSC expansion in IBD." (PMID 40244120, 2025). "In another colitis model induced with oral dextran sulfate, EO given by gavage for 11 days alleviated the clinical findings in mice and significantly decreased the gene expression levels of IL-1β, TGFβ1 and IL-6 in colon tissue." (PMID 40233022, 2025). "Accordingly, PAG resin (400 mg/kg) + honey (400 mg/kg) caused significant inhibition of the inflammation of the bowel and colonic ulcer incidence in acetic acid‐induced colitis in rats, which were represented by reduced serum inflammatory mediators (IL‐6 and TNF‐α cytokines)." (PMID 40034223, 2025). "Previous studies indicated that IL‐6 inhibition could ameliorate intestinal permeability in DSS‐induced colitis through the reduced expression of the intestinal tight junction protein, claudin‐2." (PMID 39815783, 2025). "Similarly, lower levels of IL-6, IL-8, and sCD25 were associated with the development of anti-CTLA-4-induced colitis, as demonstrated using multiplex assays." (PMID 40632185, 2025). "The synbiotic FCT (fermented milk with L. gasseri 505 and C. tricuspidata) has demonstrated concurrent upregulation of MUC2, TFF3, and tight junction proteins (occludin, ZO-1), along with significant downregulation of TNF-α, IFN-γ, IL-1β, IL-6, and iNOS/COX-2 in colitis-associated cancer models." (PMID 41395459, 2025). "Moreover, FMT significantly reduced the expression of TNF-α and IL-6 in colon tissues in ICB+DSS-induced colitis mice." (PMID 39895628, 2025). "Additionally, the UAF1 inhibitor demonstrated a significant suppression of the levels of inflammatory markers (TNF-α, IL-6, IL-17, and IL-1β) in the colon tissue of colitis mice (P < 0.05 and P < 0.01)." (PMID 39966502, 2025). "IL-6 is a pro-inflammatory cytokine that plays a role in the development of several autoimmune and chronic inflammatory conditions, including arthritis, peritonitis, and colitis." (PMID 40564167, 2025).